C9orf72 (C9orf72-SMCR8 complex subunit)
Diseases named in the same sentence as C9orf72 in open-access papers (continued):
Sharing a sentence is not in itself a finding about the gene and the disease.
frontotemporal dementia (continued). "Frontotemporal dementia (FTD) is a common cause of dementia with around one-third of cases being familial, most commonly caused by mutations in 1 of 3 genes: chromosome 9 open reading frame 72 (C9orf72), progranulin (GRN), and microtubule-associated protein tau (MAPT)." (PMID 29172163, 2018). "Intronic GGGGCC repeat expansions in C9orf72 are the most common genetic cause of amyotrophic lateral sclerosis (ALS) and frontotemporal dementia (FTD)." (PMID 28550099, 2017). "The most frequent genetic cause of amyotrophic lateral sclerosis (ALS) and frontotemporal dementia (FTD) is intronic hexanucleotide (G4C2) repeat expansions (HRE) in the C9orf72 gene." (PMID 29326544, 2017). "Translation of the expanded (ggggcc)n repeat in C9orf72 patients with amyotrophic lateral sclerosis (ALS) and frontotemporal dementia (FTD) causes abundant poly-GA inclusions." (PMID 28409281, 2017). "The C9orf72 GGGGCC repeat expansion is a major cause of amyotrophic lateral sclerosis and frontotemporal dementia (c9ALS/FTD)." (PMID 28408402, 2017). "The discovery that GGGGCC expansions in the C9orf72 gene are the most common genetic cause of amyotrophic lateral sclerosis (ALS) and frontotemporal dementia (FTD), collectively termed C9FTD/ALS, has transformed our understanding of these diseases." (PMID 28533210, 2017). "A GGGGCC repeat expansion in the first intron of C9orf72 is the most common known inherited cause of amyotrophic lateral sclerosis and frontotemporal dementia (C9ALS/FTD)." (PMID 27776165, 2016). "C9orf72 is the most common genetic cause of amyotrophic lateral sclerosis (ALS) and frontotemporal dementia (FTD) in Caucasian populations." (PMID 27375918, 2016). "Hexanucleotide repeat expansion in an intron of Chromosome 9 open reading frame 72 (C9orf72) is the most common genetic cause of Amyotrophic Lateral Sclerosis (ALS) and Frontotemporal Dementia (FTD)." (PMID 27774051, 2016). "The presence of repeated nucleotides in the non-coding region of the C9orf72 gene (GGGGCC) has been linked to the neurodegenerative diseases Amyotrophic Lateral Sclerosis (ALS) and Frontotemporal dementia (FTD)." (PMID 27875531, 2016). "Abnormal expansions of an intronic hexanucleotide GGGGCC (G4C2) repeat of the C9orf72 gene are the most common genetic cause of amyotrophic lateral sclerosis (ALS) and frontotemporal dementia (FTD)." (PMID 26564809, 2015). "In addition, although the A239T tau variant is reported to be benign, a recent study identified this mutation in a patient carrying a repeat expansion in the C9ORF72 gene, which is the most common cause of amyotrophic lateral sclerosis (ALS) and frontotemporal lobar degeneration (FTLD)." (PMID 26276810, 2015). "Double-R-loop formation and processing to instability was extended to the expanded C9orf72 (GGGGCC)·(GGCCCC) repeats, known to cause amyotrophic lateral sclerosis and frontotemporal dementia, providing the first suggestion through which these repeats may become unstable." (PMID 25147206, 2014). "Numerous families exhibiting both frontotemporal dementia (FTD) and amyotrophic lateral sclerosis (ALS) have been described, and although many of these have been shown to harbour a repeat expansion in C9ORF72, several C9ORF72-negative FTD-ALS families remain." (PMID 23338750, 2013). "We aimed to accurately estimate the frequency of a hexanucleotide repeat expansion in C9orf72 that has been associated with a large proportion of cases of amyotrophic lateral sclerosis (ALS) and frontotemporal dementia (FTD)." (PMID 22406228, 2012). "One of the identified genetic factors underlying neurological disorders, such as amyotrophic lateral sclerosis (ALS) and frontotemporal dementia (FTD), involves a significant expansion of GGGGCC (G4C2) repeats within the C9orf72 gene (Brčić and Plavec 2017)." (PMID 39829311, 2025).
frontotemporal dementia (continued). "C9orf72 (i.e., open reading frame gene 72 on chromosome 9) contains a hexanucleotide repeat expansion (GGGGCC) responsible for ALS and frontotemporal dementia." (PMID 40283201, 2025). "Hexanucleotide repeat expansions in a non-coding region of C9orf72 are predominantly seen in ~40% of fALS cases and 5–10% sALS, as well as ALS with frontotemporal dementia (FTD)." (PMID 41009796, 2025). "Here we describe the generation and validation of lines carrying the most common causative mutation for amyotrophic lateral sclerosis (ALS) and frontotemporal dementia (FTD), a repeat expansion in the C9orf72 gene, for the iNDI collection of neurodegenerative iPSC models." (PMID 41030957, 2025). "Later polyGR RAN proteins were shown to be expressed from the C9orf72 G4C2•G2C4 repeat expansion mutation and accumulate as aggregates in the brain and spinal cord of amyotrophic lateral sclerosis and frontotemporal dementia (C9-ALS/FTD) patients." (PMID 41204969, 2025). "Nonetheless, Boeve & Graff-Radford found different degrees of impairment of cognitive abilities, including the visuospatial ones, in patients with C9orf72 repeat expansions showing ALS and/or the frontotemporal dementia phenotype (c9FTD/ALS)." (PMID 40057753, 2025). "Moreover, mutations in the C9orf72 gene, recognized as the most common genetic cause of familial ALS and frontotemporal dementia (FTD), have also been linked to aberrant IFN signaling." (PMID 41359111, 2025). "This GGGGCC repeat expansion in the noncoding region of the C9ORF72 gene is the most common genetic abnormality in familial and sporadic ALS- and frontotemporal dementia (FTD)." (PMID 38534355, 2024). "The link between ALS and frontotemporal lobar degeneration (FTLD) is actually well acknowledged, especially in C9orf72 carriers." (PMID 38802624, 2024). "The most common of these is a -(G4C2)n- nucleotide repeat expansion (NRE) in a non-coding region of the C9orf72 gene (C9), which accounts for up to 20% of all ALS cases, as well as a subset of frontotemporal dementia (FTD) cases." (PMID 38684907, 2024). "Researchers using Cynomolgus monkeys have been able to create a primate model of C9orf72 related dipeptide repeats (DPRs) and show that poly (PR) DPRs are sufficient to induce C9-ALS/frontotemporal dementia (FTD)-like symptoms in primates." (PMID 39280794, 2024). "Furthermore, SVs have demonstrated the ability to modulate gene expressions and have already been implicated in neurodegenerative diseases, such as the C9orf72 repeat expansion in ALS and frontotemporal dementia (FTD)." (PMID 38540776, 2024). "Neuropathological features of frontotemporal dementia and amyotrophic lateral sclerosis (ALS) due to C9orf72 GGGGCC hexanucleotide repeat expansion include early dipeptide repeats, repeat RNA foci, and subsequent TDP-43 pathologies." (PMID 36793534, 2023). "Up to 15% of ALS patients also develop signs of frontotemporal dementia (FTD) and several genes, including C9ORF72, TDP-43, VCP, SQSTM1, OPTN, UBQLN2 and TBK1, contribute to the etiology of both ALS and FTD." (PMID 37220877, 2023). "In ALS and frontotemporal dementia (FTD), AFF2/FMR2 regulates the expression of the C9orf72 allele containing G-rich sequences, and knockdown of AFF2/FMR2 decreases the expression of the mutant allele, resulting in the rescue of axonal degeneration and TDP-43 pathology." (PMID 37323535, 2023). "A (G4C2)n hexanucleotide repeat expansion (HRE) in the C9orf72 gene accounts for 30–50% of FALS, as well as 5–10% of SALS cases, and represents the most common genetic defect in ALS and in frontotemporal dementia (FTD)." (PMID 36308529, 2023). "Hexanucleotide repeat expansions in C9orf72 account for a large proportion of cases of amyotrophic lateral sclerosis (ALS) and frontotemporal lobar degeneration." (PMID 35746899, 2022).
frontotemporal dementia (continued). "A third of frontotemporal dementia (FTD) is caused by an autosomal-dominant genetic mutation in one of three genes: microtubule-associated protein tau (MAPT), chromosome 9 open reading frame 72 (C9orf72) and progranulin (GRN)." (PMID 35348856, 2022). "Frontotemporal dementia (FTD) is a common form of young-onset dementia and is frequently caused by autosomal dominant genetic mutations in progranulin (GRN), chromosome 9 open reading frame 72 (C9orf72) or microtubule-associated protein tau (MAPT)." (PMID 36064709, 2022). "Rationale: A C9orf72 hexanucleotide repeat expansion (GGGGCC) is the most common genetic origin of amyotrophic lateral sclerosis (ALS) and frontotemporal dementia (FTD)." (PMID 36438488, 2022). "For example, the (GGGGCC)n hexanucleotide repeat expansion in intron 1 of C9orf72 is a major cause of ALS (amyotrophic lateral sclerosis) and FTD (frontotemporal dementia) and the (GGGGCC)n sequester hnRNP H RBP and generates insoluble polypeptides specific to FTD/ALS." (PMID 35723340, 2022). "Perhaps the most causal relationship with malfunctioning GTPase proteins and neurodegeneration can be implicated in familial Frontotemporal Dementia (FTD) and Amyotrophic lateral sclerosis (ALS), where the gene product of C9ORF72 presents a Rho GTPase GEF activity." (PMID 34054432, 2021). "Our knowledge is increasing regarding the role and underlying mechanism of C9ORF72 in the pathogenesis of various neurodegenerative diseases, such as amyotrophic lateral sclerosis (ALS), frontotemporal dementia (FTD), Parkinson's disease (PD), and Alzheimer's disease (AD)." (PMID 33390807, 2021). "Here we developed a repeat-specific form of hybridization chain reaction (R-HCR) as an alternative method for detection of repeat RNA foci in two neurodegenerative disorders: C9orf72 associated ALS and frontotemporal dementia (C9 ALS/FTD) and Fragile X-associated tremor/ataxia syndrome." (PMID 33892814, 2021). "Since the discovery of a repeat expansion in the C9orf72-SMCR8 complex subunit (C9orf72), researchers have worked diligently to unravel the mechanisms underlying C9orf72-related diseases, including amyotrophic lateral sclerosis (ALS) and frontotemporal dementia (FTD)." (PMID 32000838, 2020). "A repeat expansion in the C9orf72 gene is associated with two neurodegenerative disorders, which represent the extremes of a disease spectrum: amyotrophic lateral sclerosis (ALS) and frontotemporal dementia (FTD)." (PMID 32876811, 2020). "A repeat expansion mutation in the C9orf72 gene is the most frequent cause of familial amyotrophic lateral sclerosis (ALS) and familial frontotemporal dementia (FTD) in populations of Northern European origin accounting for 5–10% of sporadic cases of these disorders." (PMID 33329355, 2020). "Next, we screened the genes related to Perry syndrome, frontotemporal dementia (FTD), such as DCTN1, and MAPT by Sanger sequencing and C9orf72 by the repeat-primed PCR." (PMID 32854784, 2020). "Expansion of a (G4C2)n repeat in C9orf72 causes amyotrophic lateral sclerosis (ALS) and frontotemporal dementia (FTD), but the link of the five repeat-encoded dipeptide repeat (DPR) proteins to neuroinflammation, TDP-43 pathology, and neurodegeneration is unclear." (PMID 32562018, 2020). "A GGGGCC (G4C2) hexanucleotide repeat expansion (HRE) in chromosome nine open reading frame 72 (C9orf72) is the most common genetic cause of amyotrophic lateral sclerosis (ALS) and frontotemporal dementia (FTD), accounting for up to 40% of cases of familial ALS." (PMID 33300868, 2020). "The large expansion of GGGGCC (G4C2) repeats of the C9orf72 gene have been found to lead to the pathogenesis of devastating neurological diseases, amyotrophic lateral sclerosis (ALS) and frontotemporal dementia (FTD)." (PMID 29402965, 2018).
frontotemporal dementia (continued). "Since the discovery of the (GGGGCC)n repeat expansion in C9orf72 in about 10% of amyotrophic lateral sclerosis (ALS) and frontotemporal dementia patients, several potential pathomechanisms have been proposed." (PMID 30456350, 2018). "Upto 15% of ALS patients are also diagnosed with frontotemporal dementia (FTD) and segregation of both ALS and FTD may be seen within families, particularly those with mutations in C9ORF72 (refs 7, 8)." (PMID 27080313, 2016). "Expansion mutations in the C9orf72 gene may cause amyotrophic lateral sclerosis (ALS), frontotemporal dementia (FTD), or mixtures of the two clinical phenotypes." (PMID 27995069, 2016). "Frontotemporal Dementia (FTD), is a well established, disorder having some features similar to ALS, an observation underscored by the discovery of a hexanucleotide repeat expansion in the first intron of the C9ORF72 gene on chromosome 9p21 associated with both ALS and FTD." (PMID 25294995, 2014). "Because of the high prevalence of C9orf72 mutations in cases of ALS, and because mutations in C9orf72 have also been associated with other neurodegenerative disorders, such as Parkinson’s disease and frontotemporal dementia (FTD), C9orf72 is a promising candidate for targeted antisense therapy." (PMID 25562650, 2013). "A hexanucleotide (GGGGCC) repeat expansion in the first intron of the C9orf72 gene was recently identified as a major contributing factor to the chromosome 9p21-linked diseases amyotrophic lateral sclerosis (ALS) and frontotemporal dementia (FTD)." (PMID 24068985, 2013). "Individuals carrying (GGGGCC) expanded repeats in the C9orf72 gene represent a significant portion of patients suffering from amyotrophic lateral sclerosis (ALS) and frontotemporal dementia (FTD)." (PMID 24166615, 2013). "C9orf72 positive FTD (c9FTD) cases may show clinically typical FTD features and have been described to most commonly present with behavioural variant frontotemporal dementia, often with prominent psychiatric and amnestic symptoms." (PMID 23818065, 2013). "GGGGCC repeat expansions in the C9orf72 gene have been identified as a major contributing factor in patients with amyotrophic lateral sclerosis (ALS) and frontotemporal dementia (FTD)." (PMID 24068985, 2013). "Recently, mechanisms of early ER stress were investigated using iPSCs-derived motor neurons from C9orf72-ALS/FTD patients who had a monogenic form of ALS due to a hexanucleotide repeat expansion in their C9orf72 gene, along with symptoms of frontotemporal dementia (FTD)." (PMID 40649921, 2025). "Alterations in these processes have been widely reported among studies investigating the toxic function of dipeptide repeats (DPRs) produced by G4C2 expansion in the C9orf72 gene of patients with amyotrophic lateral sclerosis (ALS) and frontotemporal dementia (FTD)." (PMID 38247869, 2024). "Interestingly, ATXN2 also serves as a major modifier of ALS, with significant interactions observed between ATXN2 and pathologically expanded HRE-induced C9orf72 deletions, leading to ALS-frontotemporal dementia (ALS-FTD) pathogenesis." (PMID 39039334, 2024). "Advancements in understanding the pathogenesis of C9orf72-associated frontotemporal dementia (C9orf72-FTD) have highlighted the role of repeat-associated non-ATG (RAN) translation and dipeptide repeat proteins (DPRs), with Drosophila melanogaster models providing valuable insights." (PMID 38915937, 2024). "Histopathologically, there is parallel evidence of changes in the hypothalamus and hypophysis: toxic protein aggregations of pTDP-43 and dipeptide repeats in C9orf72-related ALS and ALS with frontotemporal dementia (ALS-FTD) have been found in the hypothalamic–pituitary axis." (PMID 36853389, 2023).
frontotemporal dementia (continued). "In this study, we investigated a panel of CSF synaptic markers in presymptomatic and symptomatic people with genetic FTD from the GENetic Frontotemporal dementia Initiative (GENFI), hypothesizing that we would find differential abnormalities across MAPT, GRN, and C9orf72 mutation carriers." (PMID 36045450, 2022). "Consistently, expansion of a hexanucleotide repeat (GGGGCC) in the C9orf72 gene of patients with familial ALS and frontotemporal dementia decreases C9orf72 protein expression and induces type I IFN response in blood-derived macrophages, whole blood, and brain tissue in a STING-dependent manner." (PMID 35084490, 2022). "Modeling of such disorders can be exemplified by chromosome 9 open reading frame 72 (C9orf72)-related ALS and frontotemporal dementia (FTD) when repeat-containing non-coding sequences are used as transgenes and generated in the cells via AAV-mediated transcription." (PMID 35625877, 2022). "Characteristically, pedigrees in which the mutated allele of C9orf72 segregated from one generation to another, showed different affected phenotypes, ranging from amyotrophic lateral sclerosis (ALS) to frontotemporal dementia (FTD) sometimes with peculiar features." (PMID 35754952, 2022). "While direct molecular hallmarks of the C9orf72 HRE (repeat RNA foci, dipeptide repeat protein pathology) are well characterized, the mechanisms by which the C9orf72 HRE causes ALS and the related neurodegenerative disease frontotemporal dementia (FTD) remain poorly understood." (PMID 33741069, 2021). "Some 20% of ALS cases, mostly bearing the C9orf72 hexanucleotide repeat extension, develop frontotemporal lobar degeneration (FTLD) and progressive cognitive decline with behavioural changes subsequently leading to clinical frontotemporal dementia (FTD)." (PMID 34830074, 2021). "Nucleolar stress has been implicated in the pathology and disease pathogenesis of amyotrophic lateral sclerosis (ALS) and frontotemporal lobar degeneration (FTLD) from repeat expansions of GGGGCC in C9orf72 (C9-ALS/FTLD) but not in sporadic ALS (SALS)." (PMID 33588953, 2021). "At the C9orf72 locus, a hexanucleotide repeat expansion with 100% GC content (GGGGCC) can expand into the hundreds, and even thousands, of repeats, and is the most common heritable cause of both amyotrophic lateral sclerosis (ALS) and frontotemporal dementia (FTD)." (PMID 32721467, 2021). "Two patients enrolled in the study and without a family history for ALS or frontotemporal dementia showed the GGGGCC hexanucleotide expansion in the first intron of C9orf72." (PMID 32546239, 2020). "In this study, our aim was to evaluate potential peripheral inflammatory changes in frontotemporal lobar degeneration (FTLD) patients carrying or not the C9orf72 repeat expansion." (PMID 31559531, 2020). "In addition, No-Amp approach has been utilized to successfully sequence across C9orf72 and ATXN10 repeat expansion loci in patients with frontotemporal dementia or Parkinson’s disease, respectively." (PMID 31134132, 2019). "An increase in the number of d(G4C2)•(G2C4) nucleotide repeats (repeat expansion) in the non-coding region of C9orf72 gene has been identified as the most common genetic cause of two devastating neurological disorders, amyotrophic lateral sclerosis (ALS) and frontotemporal dementia (FTD)." (PMID 30277522, 2018). "The most common known mutation associated with ALS/frontotemporal dementia (FTD) is a G4C2 hexanucleotide DNA repeat expansion in the non-coding region of C9ORF72, accounting for at least 10% of all ALS/FTD (up to 40% of familial cases, at least 10% of sporadic cases)." (PMID 28516330, 2017). "In particular, C9ORF72 gene has been defined as the most common mutation in SALS and FALS, representing up to 6% and up to 40% respectively, with or without frontotemporal dementia (FTD)." (PMID 25157374, 2014).